NCAPG (non-SMC condensin I complex subunit G)
Diseases named in the same sentence as NCAPG in open-access papers (continued):
Sharing a sentence is not in itself a finding about the gene and the disease.
glioma (continued). "Next, we explored the relationship between the expression level of NCAPG and the biological properties of glioma using LN-229 and T98G cell lines." (PMID 35372056, 2022). "Based on multivariate Cox analysis, a nomogram was constructed to predict the prognosis of patients with glioma based on the expression of NCAPG and to stratify glioma patients with better performance." (PMID 35280743, 2022). "The relationship between NCAPG expression and the infiltration of immune cells in glioma was assessed in the Tumor Immune Estimation Resource (TIMER) database." (PMID 35280743, 2022). "In conclusion, this study revealed the high expression of NCAPG in glioma tissues through comprehensive RNA-seq analysis." (PMID 35372056, 2022). "To further verify the role of NCAPG in the progression of glioma, we used the TCGA dataset to explore the relationship between the expression level of the NCAPG gene, patient survival, tumor classification, and isocitrate dehydrogenase (IDH) mutations." (PMID 35372056, 2022). "The expression level of NCAPG in glioma can reflect, to a certain extent, the tumor grade and prognosis of patients." (PMID 35372056, 2022). "In summary, the findings of this study showed that NCAPG expression was increased in glioma tissues and that its high expression correlated with malignant progression of gliomas." (PMID 35280743, 2022). "Overall, these results demonstrated that increased NCAPG expression correlated significantly with glioma tumorigenesis and progression." (PMID 35280743, 2022). "Evaluation of the effects of NCAPG knockdown on the migration ability of glioma cells, as determined by transwell and wound healing assays, showed that knockdown of NCAPG inhibited cell migration." (PMID 35280743, 2022). "Transwell invasion assays were conducted to evaluate the effects of NCAPG silencing on the invasive abilities of glioma cells (LN-229 and T98G)." (PMID 35372056, 2022). "The results showed the significance of NCAPG expression in determining glioma prognosis and tumor grade." (PMID 35372056, 2022). "Higher expression of NCAPG in gliomas correlated with poorer prognosis, unfavorable histological features, absence of mutations in the isocitrate dehydrogenase gene (IDH), absence of chromosome 1p and 19q deletions, and responses to chemoradiotherapy." (PMID 35280743, 2022). "Analysis of the expression of NCAPG in immune subtypes of glioma showed that NCAPG was mainly highly expressed in the C4 subtype." (PMID 35280743, 2022). "The biological functions of NCAPG in these cells were evaluated by NCAPG knockdown, which significantly inhibited glioma cell proliferation and migration." (PMID 35280743, 2022). "This study aimed to evaluate NCAPG expression in glioma tissues and investigate the role of NCAPG in the development and prognosis of glioma." (PMID 35372056, 2022). "Additional studies are required to assess the function of NCAPG in glioma metastasis and in regulating the glioma tumor microenvironment." (PMID 35280743, 2022). "NCAPG silencing (si-NCAPG group) significantly decreased the proliferation of glioma cells (LN-229 and T98G) in contrast with the respective si-NC groups." (PMID 35372056, 2022). "These analyses confirmed that OS was lower in patients with high than low NCAPG expression, indicating that high expression of NCAPG is likely an indicator of poor prognosis in glioma patients." (PMID 35280743, 2022). "NCAPG knockdown in glioma cell lines significantly reduced cell survival, proliferation, and migration." (PMID 35280743, 2022). "NCAPG expression was significantly higher in glioma tissue than in adjacent normal tissue (P < 0.001); these results were verified by evaluation of datasets from the GEO, Rembrandt, and Gravendeel databases." (PMID 35280743, 2022). "Taken together, these findings suggest that NCAPG is a potential biomarker for prognosis in patients with glioma." (PMID 35280743, 2022).
glioma (continued). "Subsequently, gene ontology (GO) analysis and gene set enrichment analysis (GSEA) were performed to determine the possible biological functions and pathways of NCAPG in glioma." (PMID 35280743, 2022). "Cox and univariate analyses showed that NCAPG expression correlated positively with WHO grade, primary therapy outcome, IDH mutation status, age, and poor OS in patients with glioma." (PMID 35280743, 2022). "The functions of NCAPG in glioma were assessed using LinkedOmics to determine genes co-expressed with NCAPG." (PMID 35280743, 2022). "In addition, the role of NCAPG in glioma expression was analyzed experimentally by immunohistochemistry (IHC), qRT-PCR, and by growth curve, transwell and wound healing assays." (PMID 35280743, 2022). "In addition, using Cox analysis, we identified that the expression level of NCAPG in glioma can serve as an independent prognostic factor in glioma patients." (PMID 35372056, 2022). "In addition, Cox regression analysis showed that NCAPG can act as an independent prognostic factor and as a tumor marker for glioma." (PMID 35372056, 2022). "Knockdown of NCAPG in glioma cells reduced their proliferation and migration activities." (PMID 35280743, 2022). "In addition, overexpression of NCAPG was found to promote the proliferation, migration, and differentiation of glioma cells." (PMID 35372056, 2022). "In addition, the correlations of NCAPG expression with immune cell infiltration and glioma progression were analyzed." (PMID 35280743, 2022). "Assessment of the prognostic value of NCAPG expression in glioma patients subgrouped by histological type, sex, IDH mutation status, WHO grade, chromosome 1p/19q co-deletion, and age showed that high expression of NCAPG was associated with poor prognosis in all of these groups." (PMID 35280743, 2022). "Furthermore, the expression of NCAPG increased significantly with the increase in tumor grade, and high NCAPG expression was found to be a predictor of poor overall survival in glioma patients (P < 0.001)." (PMID 35372056, 2022). "Our study is first in comprehensively describing the high expression of NCAPG in glioma." (PMID 35372056, 2022). "NCAPG expression was higher in gliomas than in adjacent normal tissues." (PMID 35280743, 2022). "Evaluation of the correlations between NCAPG expression and the clinical characteristics of glioma patients, as determined by datasets from the CGGA, TCGA, Gravendeel, and Rembrandt databases showed that increased NCAPG expression was associated with higher WHO grade classification." (PMID 35280743, 2022). "High expression levels of NCAPG were significantly correlated with poor survival in glioma patients, and could also enhance the proliferation, migration, and invasion ability of glioma cells." (PMID 35372056, 2022). "Moreover, NCAPG expression was positively correlated with immune cell infiltration into gliomas in general and with the infiltration of B cells, CD4+ T cells, CD8+ T cells, macrophages, neutrophils, and dendritic cells in glioma." (PMID 35280743, 2022). "Analysis of immune cell infiltration in the present study showed that high NCAPG expression was significantly and positively associated with levels of B cells, CD8+ T cells, CD4+ T cells, macrophages, neutrophils, and dendritic cells in gliomas." (PMID 35280743, 2022). "The level of expression of NCAPG protein was found to increase with increasing glioma grade." (PMID 35280743, 2022). "Taken together, these results suggest that NCAPG might affect immune cell infiltration, making NCAPG expression a predictive biomarker for the effects of immunotherapy in patients with glioma." (PMID 35280743, 2022). "In addition, our study demonstrated that the expression of ADAM17 in the glioma cell lines was positively correlated with the expression of NCAPG." (PMID 35372056, 2022). "Therefore, further studies on NCAPG will be helpful for the diagnosis and treatment of glioma in the future." (PMID 35372056, 2022).
glioma (continued). "In summary, NCAPG can determine the prognosis and act as a new biomarker for glioma." (PMID 35372056, 2022). "Furthermore, we analyzed the relationship between the expression of NCAPG in glioma and the survival time of glioma patients, tumor classification, and IDH mutation using TCGA data." (PMID 35372056, 2022). "Furthermore, we also found that the expression level of NCAPG was more or less related to the grade of the glioma, and that high NCAPG expression usually corresponded to high-grade tumor samples." (PMID 35372056, 2022). "Moreover, NCAPG expression was significantly higher in glioma patients after than before treatment with radiotherapy and/or chemotherapy." (PMID 35280743, 2022). "We found that NCAPG was significantly overexpressed in gliomas and that increased NCAPG expression correlated significantly with poor outcomes, tumor grade, age, IDH mutation status, and chromosome 1p/19q co-deletion status, as well as with the outcomes of radiotherapy and chemotherapy." (PMID 35280743, 2022). "GSEA tools were utilized to identify the signaling pathways involving NCAPG in glioma." (PMID 35280743, 2022). "NCAPG expression correlates with glioma progression and immune cell infiltration, suggesting that NCAPG expression may be a useful prognostic biomarker for glioma." (PMID 35280743, 2022). "Overall, these results confirmed that NCAPG could serve as a potential novel prognostic biomarker in patients with glioma." (PMID 35280743, 2022). "It has been reported that NCAPG knockdown combined with temozolomide could inhibit the proliferation of pediatric high-grade gliomas." (PMID 35292013, 2022). "Because GSEA showed that NCAPG expression correlated with the immune response-related signaling pathway, we further examined the correlation between NCAPG expression and immune cell infiltration in glioma tissues." (PMID 35280743, 2022). "The expression of NCAPG in GBM was significantly higher than that in other pathological gliomas." (PMID 35372056, 2022). "In the present study, we found that NCAPG was significantly overexpressed in glioma by analyzing the RNA-seq datasets of 698 gliomas obtained from The Cancer Genome Atlas (TCGA) network and 433 gliomas obtained from the Gene Expression Omnibus (GSE4290 and GSE16011) database." (PMID 35372056, 2022). "However, this study did not involve in vivo experiments, which will be included in a follow-up study to explore in depth the specific mechanism of NCAPG regulation of the immune microenvironment, and attempt to use NCAPG as a target for glioma treatment to evaluate its therapeutic effect." (PMID 35372056, 2022). "In summary, NCAPG may act as an independent prognostic factor for gliomas." (PMID 35372056, 2022). "However, the exact role of NCAPG in glioma, and more generally in cancer, remains to be determined." (PMID 35372056, 2022). "In addition, we showed that depletion of NCAPG could inhibit the cell migration of glioma cells, the potential molecular mechanisms of NCAPG in cancer metastasis remain unclear." (PMID 35280743, 2022). "However, the function of NCAPG in glioma remains incompletely understood." (PMID 35280743, 2022). "Moreover, glioma patients with wild-type IDH exhibited an increased expression of NCAPG." (PMID 35372056, 2022). "However, the pattern of NCAPG expression, its prognostic value, and its correlation with the tumor microenvironment in glioma remain unclear." (PMID 35280743, 2022). "NCAPG was positively correlated with cell cycle, DNA damage, DNA repair, EMT, invasion, metastasis, and proliferation in glioma." (PMID 41438761, 2025).
glioma (continued). "Using TIMER database analysis, we found that alterations in the somatic copy number of NCAPG correlated significantly with infiltration of B cells, CD4+ T cells, CD8+ T cells, neutrophils, macrophages, and dendritic cells into gliomas." (PMID 35280743, 2022). "Based on the TCGA and CGGA data of glioma tissues, we found that the expression of MHC-I molecules increased with the increase in NCAPG expression." (PMID 35372056, 2022). "Subsequently, we identified a positive correlation between the expression of NCAPG and MHC-I molecules in the glioma cell lines (LN-229 and T98G)." (PMID 35372056, 2022). "First, we analyzed the relationship between the expression of NCAPG and major histocompatibility complex-I (MHC-I) using the TCGA and CGGA glioma datasets." (PMID 35372056, 2022). "The ability of a nomogram that included NCAPG expression, histological type, sex, IDH mutant status, WHO grade, chromosome 1p/19q co-deletion, and age to accurately predict prognosis in glioma patients was tested." (PMID 35280743, 2022). "Therefore, this study explored the relationship between the expression of NCAPG and glioma, illustrated the relationship between the expression of NCAPG and the glioma immune microenvironment, and explored the mechanism by which NCAPG affects NK cell activation in glioma." (PMID 35372056, 2022). "First, we comprehensively analyzed the TCGA-glioma and GEO (GSE 10611 and 4290) datasets and detected a high expression of NCAPG in glioma; we then verified the results using the GEPIA online website." (PMID 35372056, 2022). "Currently, studies have shown that the subunits of condensin, such as NCAPG, SMC4, and NCAPG2, have been reported to be involved in the glioma pathogenesis." (PMID 35992200, 2022). "We demonstrated that miR-137 and miR-6500-3p exhibit anti-tumor activity in pediatric glioma cell lines by blocking CENPE, KIF14 or NCAPG expression." (PMID 26933822, 2016). "We validated the results using the Chinese Glioma Genome Atlas (CGGA) database and determined that the NCAPG gene could be further investigated as an independent prognostic factor for glioma." (PMID 35372056, 2022). "Furthermore, we tested the expression of α-disintegrin and metalloprotease-17 (ADAM17) in glioma tissues and found that the expression of ADAM17 decreased with the reduction in NCAPG expression." (PMID 35372056, 2022). "Non-SMC condensin I complex subunit G (NCAPG) is expressed in various human cancers, including gliomas." (PMID 35280743, 2022). "The results showed that NCAPG was highly expressed in glioma tissues, while it was almost absent in normal tissues." (PMID 35372056, 2022). "Although we explored the correlation between NCAPG and immune cell infiltration in glioma patients, we did not determine the function of NCAPG in regulating the tumor microenvironment in glioma." (PMID 35280743, 2022). "Unfortunately, there is still no research to clarify how NCAPG regulates the cell cycle and how to promote glioma progression by affecting the 3D genome structure of glioma." (PMID 35992200, 2022). "Importantly, when the expression of NCAPG was knocked down, the CCK-8 assay revealed that the proliferation of glioma cells (LN-229 and T98G cell lines) decreased significantly compared with the control group." (PMID 35372056, 2022). "Overall, we can conclude that the expression of NCAPG in glioma is relatively high, and that the expression of MHC-I molecules and ADAM17 in glioma cells is also elevated, thereby inhibiting the activation of NK cells, resulting in immune escape and decreased patient survival." (PMID 35372056, 2022). "In addition, we found several hub genes with worse OS and higher expression level in glioma patients, including VEGFA, NDC80, TIMP1, SAA1, CENPA, CENPF, and NCAPG and we firstly found relationship of SAA1, TIMP1, and molecular pathology in GBM." (PMID 30867991, 2019).
glioma (continued). "We conducted a correlation analysis between the expression levels of NCAPG in tumors and 22 types of immune cells in the immune microenvironment using the TCGA-glioma data set, and found a negative relationship between the expression of NCAPG and NK cell activation, which attracted our attention." (PMID 35372056, 2022). "Furthermore, the present study assessed the expression and biological roles of NCAPG in databases of patients with glioma and cultured cells, not in vivo." (PMID 35280743, 2022). "However, the expression level of NCAPG in glioma was not correlated with the sex of the patient or the expression levels of Ki-67 and GFAP." (PMID 35372056, 2022). "Furthermore, qRT-PCR assays showed that NCAPG was highly expressed in glioma cell lines, especially in A172 and U251 cells, but not in normal human astrocytes." (PMID 35280743, 2022). "However, whether NCAPG can be used as a biomarker of glioma and its function in gliomas have not yet been reported." (PMID 35372056, 2022).
gastric cancer (16 papers, 2018 to 2024). A primary or metastatic malignant neoplasm involving the stomach. "For example, increased expression of NCAPG has been associated with a poor prognosis in patients with gastric cancer." (PMID 35280743, 2022). "Meanwhile, NCAPG, another subunit of condensin I, has been reported to regulate the G1 phase in gastric cancer, which may further support the novel function of condensin I in the interphase." (PMID 34768935, 2021). "Dysregulation of NCAPG may contribute to the progression of gastric cancer." (PMID 31788359, 2019).
lung cancer (14 papers, 2017 to 2024). A malignant neoplasm involving the lung. "However, the biological function and underlying mechanism of NCAPG in non–small cell lung cancer (NSCLC) are still unclear." (PMID 35211508, 2021). "We analyzed lung cancer cohorts with KRAS mutations (GSE31210) and found that higher hub gene levels (BUB1, BUB1B, NCAPG, CDC20, CDK1, KIF11) were significantly associated with worse OS in lung cancer patients with KRAS mutations." (PMID 36176446, 2022). "We found that NCAPG played a significant role in lung tumorigenesis of a urethane-induced murine lung cancer model." (PMID 35180865, 2022). "Here, we take the lead to review that up-regulation of NCAPG was positively correlated with the immune cell infiltration in lung cancer." (PMID 35211508, 2021). "To examine the protein expression of NCAPG in NSCLC, we utilized an IHC assay to examine the expression of NCAPG in lung cancer." (PMID 35211508, 2021). "The results verify that the elevated expression of NCAPG was observed in lung cancer than the normal tissues." (PMID 35211508, 2021). "Moreover, the knockdown of NCAPG inhibits the proliferation, migration, and invasion of non‐small cell lung cancer (NSCLC) cells, and NCAPG overexpression is negatively associated with the survival of patients with NSCLC." (PMID 39046429, 2024). "In lung cancer, NCAPG expression activates TGF-β signaling pathway." (PMID 36996493, 2023). "NCAPG has been found as a stimulative for cardia adenocarcinoma, endometrial cancer, lung cancer." (PMID 35963640, 2022). "Additionally, we investigated the function of NCAPG on tumorigenesis of NSCLC by knocking it out in a murine lung cancer model." (PMID 35180865, 2022). "In addition to our findings on LMO1, we identified five genes (GNG4, NCAPG, SPC25, ASPM and KIF2C) that are expressed at higher levels in lung tumors relative to NATs and are significantly correlated with poor survival of lung cancer patients, suggesting possible oncogenic functions in lung cancer." (PMID 30038707, 2018).